CD4 (CD4 molecule)
Diseases named in the same sentence as CD4 in open-access papers (continued):
Sharing a sentence is not in itself a finding about the gene and the disease.
intestinal parasitic infections (20 papers, 2009 to 2025). "In this study, from clinical findings, having CD4 counts <200 cells/mm3 was the only factor significantly associated with intestinal parasitic infection." (PMID 39664543, 2024). "Factors such as a low CD4 count, consumption of unwashed raw vegetables, and rural residence are associated with increased risk of intestinal parasite infections." (PMID 39664543, 2024). "Another study in Ethiopia reported that a CD4 count of less than 500 cells/mm3 was significantly associated with opportunistic intestinal parasitic infections." (PMID 39664543, 2024). "In multivariate logistic regression analysis only hand washing habit after latrine, CD4 cell count of less than 200cells/ml3 and habit of eating raw vegetables had statistical significant association with intestinal parasitic infection." (PMID 35443715, 2022). "Bivariate analysis showed that hand washing habit after latrine, habit of eating raw vegetables, eating raw meat and CD4 count showed statistical significant association with intestinal parasitic infection." (PMID 35443715, 2022). "Having CD4+ T-cell count <200cells/μl were statistically associated with intestinal parasitic infection." (PMID 33382867, 2020). "CD4+ T-cell count <200cells/μl, unavailability of a latrine, and history of diarrhea were significantly associated with intestinal parasitic infections." (PMID 33382867, 2020). "CD4+ T-cell count <200 cells/ul, unavailability of a latrine, and history of diarrhea were significantly associated with intestinal parasitic infection." (PMID 33382867, 2020). "Therefore, the reduction in CD4+ T cell count by the HIV virus predisposes HIV-infected patients to these opportunistic intestinal parasitic infections." (PMID 26754404, 2016). "In the multivariable model excluding CD4+ count, this association was confirmed, and a previous gonococcal infection also remained independently associated with intestinal protozoa infection, reinforcing the link between sexual risk behaviors and intestinal parasitic infections." (PMID 41295589, 2025). "In this study, intestinal parasitic infection occurrence was significantly higher in patients with a CD4 count of less than 200 cells/mm3, which is in line with other study findings from different parts of Ethiopia." (PMID 39664543, 2024). "There was statistical significant association between hand washing habit after latrine, habit of eating raw vegetables and CD4 cell count less than 200 cells/ml3 and intestinal parasitic infections." (PMID 35443715, 2022). "The present study also revealed statistical significant association between hand washing habit after latrine, eating raw vegetables and CD4 cell count and intestinal parasitic infections." (PMID 35443715, 2022). "The odds of having intestinal parasitic infections were 3.5 times higher among patients having CD4+ T-cell count <200cells/μl as compared with their counterparts (AOR: 3.53, (95%CI: 1.98, 6.27))." (PMID 33382867, 2020). "The reduction in CD4 T cell count in PLWHA predisposes to intestinal parasites, especially opportunistic intestinal parasitic infections." (PMID 28506307, 2017). "Low CD4+ T cell count may appear to be a factor for intestinal parasitic infections and development of diarrhea." (PMID 26754404, 2016). "Unavailability of latrine (AOR: 4.87, (95% CI: 2.39, 9.92)), CD4+ T cell count <200cells/μl ((AOR: 3.53, (95%CI: 1.98, 6.27)), and having a history of diarrhea (AOR: 4.79 (95%CI: 1.53, 14.99) were factors significantly associated with intestinal parasitic infections." (PMID 33382867, 2020). "Likewise, it seems necessary to study this distinct action of T subsets against Encephalitozoon depending on the presence of absence of the disease since the prevalence of opportunistic intestinal parasitic infections including microsporidia is higher in patients with low CD4 cell counts." (PMID 23637975, 2013).
intestinal parasitic infections (continued). "Nevertheless, in Ethiopia, few studies have tried to investigate the extent of intestinal parasitic infections in relation to ART experiences and CD4 count." (PMID 24052888, 2013). "The overall prevalence of intestinal parasitic infections was 33.7%; it was significantly higher among the study participants who were ART-naive group (45.5%) (AOR: 2.60(1.56,4.34)) and diarrheic (53.3%) (AOR: 2.30(1.34,3.96)) and with CD4 count <200 cells/μL (46%) (AOR: 2.07(1.06,4.04))." (PMID 24052888, 2013). "Hence, this study was undertaken to determine the prevalence of Cryptosporidium and other intestinal parasite infections among HIV positives with and without Antiretroviral Treatment(ART) and its association with CD4+ T-cell count." (PMID 23991132, 2013). "Hence, this study was undertaken to determine the prevalence of intestinal parasitic infection among people with and without HIV infection and its association with diarrhea and CD4 T-cell count." (PMID 19765310, 2009). "This study showed that intestinal parasite infections are common among HIV positive patients without ART and that there exists a relationship between the type of parasite and CD4+ T-cell count." (PMID 23991132, 2013).
invasive breast carcinoma (20 papers, 2008 to 2025). A carcinoma that infiltrates the breast parenchyma. "We focus on studies demonstrating the prognostic and predictive impact of distinct tumor-infiltrating lymphocyte subpopulations including different CD8(+) T subsets as well as CD4(+) T cells and tumor-associated macrophages in invasive breast carcinoma." (PMID 40243442, 2025). "However, deletion of PINK1 was associated with substantially higher CD4+ T cell, neutrophil and dendritic cell counts in breast invasive carcinoma." (PMID 33244455, 2020). "Lastly, as CD4+ T cells are known to constitute a substantial portion of TILs in invasive breast carcinoma after CD8+ T cells, we performed immunohistochemistry for CD4 and CD8 as a baseline comparison." (PMID 39643914, 2024). "In invasive breast cancer, CD4 + T helper cells, CD8 + CTL cells, tissue-resident T cells, B cells, Natural Killer (NK) cells, M1 macrophages, and dendritic cells (DC) are protective against tumor growth (tumor-suppressing immune cells)." (PMID 34952631, 2021). "A progressive loss of circulating anti-human epidermal growth factor receptor-2/neu (HER2) CD4+ T-helper type 1 (Th1) immune responses is observed in HER2pos-invasive breast cancer (IBC) patients relative to healthy controls." (PMID 25997452, 2015). "Moreover, the Kaplan–Meier plotter data revealed that the patients with both high E2F8 mRNA levels and decreased T cells (CD4+ T cells, CD8+ T cells, and macrophage cells) had a worse RFS compared with the patients with enriched CD4+ T cells in breast invasive carcinoma." (PMID 36814821, 2023). "A positive correlation was identified between the infiltration of CD8+ T cells, CD4+ T immune cells, B cells, and other immune cells, and the expression of MPZL3 in breast invasive carcinoma (BRCA)." (PMID 39290707, 2024). "In this work, we observed that higher expression of the signature genes CD4, KLRG-1, and B3GAT1 correlated with a higher survival rate when we analyzed the OS of patients from two invasive breast carcinoma cohorts from the TCGA consortium." (PMID 34386013, 2021). "CD4+, CD8 + and FOXP3 + immune cell infiltration was significantly higher in invasive breast cancer compared to pure DCIS (p < 0.001)." (PMID 34952631, 2021). "We used immunohistochemistry to quantitate FOXP3, CD4, and CCL20 expression in 156 invasive breast cancers samples." (PMID 31852159, 2019). "High expression of GLI1 positively correlated with the abundance of infiltrating immune cells, such as DCs and CD4+ T cells, suggesting that GLI1 may partially regulate the recruitment of immune cells in the TMIE of breast invasive carcinoma." (PMID 39483334, 2024). "The comparison of the dominance of CD4 + versus CD8 + cells in pure DCIS and invasive cancer revealed that the infiltration of CD4 + TILs was higher than of CD8 + in pure DCIS (p < 0.001), while the reverse was true in invasive breast cancer with the CD8 + TILs being the dominant subset (p = 0.006)." (PMID 34952631, 2021). "Thus, in this study, we examined infiltrations of CD4+, CD8+, and FOXP3+ TILs and PD-L1+ immune cells in DCIS in relation to clinicopathologic features and compared them with those of invasive breast cancer to evaluate their changes during progression of DCIS." (PMID 32216826, 2020). "Additionally, the number of CD4+ and CD8+ T cells, the CD4/CD8 ratio at the tumor site, and CD30 expression levels are considered potential indicators for prognosis and therapeutic intervention in invasive breast carcinoma." (PMID 39869369, 2025).
ischemia (20 papers, 2011 to 2025). A hypoperfusion of the BLOOD through an organ or tissue caused by a PATHOLOGIC CONSTRICTION or obstruction of its BLOOD VESSELS, or an absence of BLOOD CIRCULATION. "In an ischemia animal model, CD4-deficient mice have impaired capability to undergo angiogenesis." (PMID 29163521, 2017). "CD4+ and Gene expression of IL-1β were significantly increased in the Ischemia group compared to the control group." (PMID 40809171, 2025). "Our study demonstrated that estrogen and progesterone significantly reduce the expression of interleukin-1β and CD4+ in the cortical region of the rats’ brain following ischemia." (PMID 40809171, 2025). "Following MCAO, the expression of IL-1β and CD4+ increased in the penumbra region of the cerebral cortex, and treatment with estrogen and progesterone modulated the adverse effects of ischemia on the cerebral cortex and decreased infarct size." (PMID 40809171, 2025). "In the Ischemia group, the expression of CD4+ increased compared to the control group (P<0.01 and P<0.0001, respectively)." (PMID 40809171, 2025). "Placental ischemia also makes CD4+ T cells increase and T regulatory cells decrease, which leads to immune imbalance in the mother and in the intrauterine environment." (PMID 38078331, 2023). "In a model of ischemia, the gastrocnemius, plantaris, and soleus muscles were treated with alginate gels containing conditioned media from different subsets of CD4+ T cells (Th1, Th2, Th17, and Treg)." (PMID 33806895, 2021). "Study reported that CD4 + T cells (including Foxp3 + Tregs) infiltrated the ischemia injury heart and promote wound healing via favorably monocytes and/or macrophage trafficking and differentiation." (PMID 33906602, 2021). "It is believed that the first local, glial immune response of the brain tissue to acute ischemia is the connection of CD4 T lymphocytes with astrocytes." (PMID 21450100, 2011). "Also, E/P administration reduced infarct volume and CD4+ and gene expression of IL-1β compared to the Ischemia group." (PMID 40809171, 2025). "In addition to T lymphocytes, NK cells and CD4 T cells have also been shown to regulate arteriogenesis in mouse ischemia models." (PMID 40842584, 2025). "Moreover, the expression of CD4+ in the EP-treated ischemia group decreased compared to the Ischemia group (P<0.05)." (PMID 40809171, 2025). "The expression of CD4+ in the ischemic penumbra in the EP-treated ischemia group decreased." (PMID 40809171, 2025). "CD4+ T cells were also found to be important in the healing of ischemia-induced muscle injuries." (PMID 33806895, 2021). "Various pro-inflammatory mediators are elevated in CD4+ T cells following ischemia." (PMID 32477327, 2020). "Infiltration of CD4+ cells has been observed within 24 h after the onset of ischemia." (PMID 32477327, 2020). "The expression of CD4+ using the immunohistochemistry (IHC) method and gene expression of IL-1β using the Real-time PCR in the ischemic penumbra of the male rat’s brain cortex were determined, and infarct volume was determined 24 hr after ischemia using TTC staining." (PMID 40809171, 2025). "For example, CD4+ FOXP3+ Treg cell delivery has been shown to reduce infarct size and attenuate MI‐induced cardiac remodeling post‐ischemia in mice." (PMID 34612564, 2021). "When administered within 24 hours of the onset of ischemia a CD147 blocking antibody reduced the number of brain infiltrating neutrophils, macrophages and both CD4 and CD8 T-cells." (PMID 32191628, 2020). "CD4+ T cells and natural killer T (NKT) cells produce IL-21, and augmented concentrations of brain IL-21 following experimental ischemia occurs after lymphocyte infiltration." (PMID 32185190, 2020). "However, the preference of the CD8+ T cells over CD4+ T cells to infiltrate across the BBB, as observed in this study, is consistent with other pro-inflammatory neuroimmune diseases as well as the results in permanent focal ischemia models." (PMID 29896429, 2018).
meningioma (20 papers, 2015 to 2025). A generally slow growing tumor attached to the dura mater. "Bulk RNA-seq analysis revealed significantly higher levels of total and CD4 + resting memory T cells in grade 2 meningiomas." (PMID 40420192, 2025). "CD4 T cells were predicted to make up significantly more of the immune compartment of VS than meningioma." (PMID 41437121, 2025). "When T cells were cocultured with siPD‐L1‐transfected NF2‐associated meningioma cells, the expression of CD69 on both CD4+ and CD8+ T cells was partly reversed, and the capacity of CD8+ T cells to kill siPD‐L1‐transfected tumor cells was partly restored." (PMID 38828669, 2024). "The results showed the presence of CD4‐positive T lymphocytes (3/13, 23.08%) and CD20‐positive B lymphocytes (6/13, 46.15%) in NF2‐associated meningiomas." (PMID 38828669, 2024). "Our study demonstrates that WHO grade 2–3 meningiomas tend to have low CD4, and CD8 expression, which has been confirmed in other studies." (PMID 36532284, 2022). "Exclusion of cytotoxic CD8+ T cells and CD4+ helper T cells are observed in high-grade meningioma, suggesting the enhanced T cells therapy is potentially treatment for recurrent meningioma." (PMID 33807688, 2021). "T cell repertoire characterization of 28 meningiomas of all grades identified populations of CD4+ and CD8+ T cells, regulatory T cells, and T cells expressing PD-1 (Programmed cell death protein 1) indicative of exhaustion." (PMID 33262459, 2021). "In anaplastic meningioma, there is a sharp decrease in the number of T cells, including the numbers of CD4+ and CD8+ T cells and cells expressing PD-1 and there is also an increase in the number of FOXP3 expressing immunoregulatory (Treg) cells." (PMID 25609200, 2015). "The percentages of CD4+CD69+ and CD8+CD69+ cells were analyzed, and the results showed that when T cells were cocultured with siPD‐L1‐transfected NF2‐associated meningioma cells, the expression of CD69 on both CD4+ and CD8+ T cells was partly reduced compared with that in the siPD‐L1‐NC group." (PMID 38828669, 2024). "A study of seven GBM patient tumor samples showed that nearly half of the GBM tumors examined were infiltrated by CD4+ T cells expressing CD56, an NK cell marker, and the frequency of CD56+CD4+ T cells was much higher than in meningiomas and metastatic lung cancers." (PMID 34208864, 2021). "Interestingly, pathway analysis based on DEGs revealed CD4 + T cells in VS compared to meningioma were predicted to be significantly more active in their signalling pathways, including those involved in cell surface interactions, activation, and cytokine release." (PMID 41437121, 2025). "In this study, we showed that among the PBTs, meningiomas had a higher percentage of CD3+, CD4+ and CD8+ T cells." (PMID 38816839, 2024). "T cells and B cells have previously been reported in meningioma using immunohistochemistry, and the proportion of CD8+ T cells was higher than the proportion of CD4+ T cells." (PMID 39682129, 2024). "CD4 and CD8 lymphocytes were all more highly expressed in WHO grade 1 meningiomas, compared to WHO grade 2–3." (PMID 36532284, 2022). "As we know, tumor-infiltrating myeloid cells in meningiomas are mainly CD3+ T cells, both CD8 and CD4, and natural killer cells, and Tregs to a lesser extent." (PMID 35892898, 2022). "A large percentage of immune cells in the meningioma microenvironment express CD45 (macrophages, myeloid derived suppressor cells, CD8+ and CD4+ T cells, and natural killer)." (PMID 35892898, 2022). "Our study also revealed that the numbers of CD4+ lymphocytes and CD163+ macrophages tended to be higher in recurrent meningiomas than in primary tumors." (PMID 33330078, 2020). "Elevated peripheral NLR was not correlated with the number of intratumoral neutrophils or CD8, CD4, or CD163+ cells in meningioma." (PMID 33330078, 2020). "The numbers of CD4 and CD163+ cells tended to be higher in recurrent meningiomas than in primary meningiomas (P = 0.057 and 0.084, respectively)." (PMID 33330078, 2020).
meningioma (continued). "In particular, we note a significant decrease in CD4+ and CD8+ T lymphocytes, a decrease in PD-1+ lymphocytes and an increase in FOXP3+ Treg lymphocytes in WHO grade III meningioma." (PMID 25609200, 2015). "CD4 + memory resting T cells were the dominant T cell subtype, indicating limited responsiveness to immune checkpoint blockade (ICB) targeting PD-1/PD-L1 in meningiomas." (PMID 40420192, 2025). "Interestingly, the activity of the significant pathways in the specific T cell subtypes differed in the two tumour types; CD4 + T cells displayed increased activity, however CD8 + T cells were predicted to be suppressed in VS compared to meningioma." (PMID 41437121, 2025). "In detail, the CD8+ (but not CD4+) CD103+ CD69+ TRM subset was significantly more abundant in GBM samples than in meningioma samples used herein as a control group." (PMID 36289717, 2022). "Further, the detection of the infiltrated immune cells in meningioma tissues showed that there was a decreased expression of CD3+, CD4+ and CD8+ T lymphocytes in malignant meningioma, which implied PD-L1 blockade may not have outstanding effect for malignant meningioma therapy." (PMID 37171006, 2023). "Conversely, the percentage and absolute values of CD4+ TRM TILs did not statistically differ between GBM and meningioma." (PMID 36289717, 2022).